GAPDH (glyceraldehyde-3-phosphate dehydrogenase)
Diseases named in the same sentence as GAPDH in open-access papers (continued):
Sharing a sentence is not in itself a finding about the gene and the disease.
glioblastoma (21 papers, 2007 to 2023). The most malignant astrocytic tumor (WHO grade IV). "Interestingly, reduction of Hsp70 synthesis in C6 rat glioblastoma cells inhibited the chaperone’s effect on GAPDH aggregation and caused increased levels of cell death." (PMID 33546324, 2021). "In the present work, we summarize the data obtained in studies of GAPDH function in hypoxia-imitating conditions and report the anti-tumor effect of AEAC, capable of dissociating GAPDH–Hsp70 interaction in cell and animal models of C6 rat glioblastoma." (PMID 33546324, 2021). "The physiological relevance of GAPDH content in glioma cells and the disruption of its chaperoning during hypoxia was studied in an in vivo glioblastoma model." (PMID 33546324, 2021). "MGMT, miR-181d and miR-603 levels were characterized for 74 glioblastoma specimens from the UCSD glioblastoma tumor bank by qRT-PCR; GAPDH was characterized as a control." (PMID 24994119, 2014). "In contrast, Said and colleagues reported that GAPDH mRNA was insensitive to lowered pO2 in glioblastoma-derived tumor cells and these findings were later confirmed in other cell lines." (PMID 21306648, 2011). "On the contrary an EGFR/GAPDH ratio ≥ 2 was obtained in a grade IV glioblastoma sample, known to have EGFR amplicons, that we used as positive control." (PMID 19196452, 2009). "Our data did not reveal any correlation between hypoxia induced HIF-1α protein overexpression and GAPDH regulation on mRNA and protein level in vitro in human glioblastoma cell lines." (PMID 17597534, 2007). "GAPDH represents an optimal choice of a housekeeping gene and/or loading control to determine the expression of hypoxia induced genes at least in glioblastoma." (PMID 17597534, 2007). "GAPDH and β-actin expression was comparatively examined in vivo in human low-grade astrocytoma and glioblastoma on both protein and mRNA level, by Western blot and semiquantitative RT-PCR, respectively." (PMID 17597534, 2007). "No regulatory effect of these different oxygenation conditions on GAPDH expression was detectable by semiquantitative RT-PCR in the human glioblastoma cell lines U251, U373 and GaMG." (PMID 17597534, 2007). "Both GAPDH and β-actin mRNA was expressed in 22/22 brain tumor samples (11 low-grade astrocytoma and 11 glioblastoma) and in 3/3 normal brain tissue samples, as shown by semiquantitative RT-PCR." (PMID 17597534, 2007). "The answer of this question will provide insight into practical applications of GAPDH as an internal standard in investigations of hypoxia-inducible gene expression or as a target for tumor therapeutic approaches in human glioblastoma." (PMID 17597534, 2007). "Furthermore, Vazquez-Blomquist investigated 18S and 28S gene stability in comparison to that of ACTB and GAPDH in glioblastoma-derived cells." (PMID 37568514, 2023). "We next tested whether the abundance of GAPDH mRNA, 18S rRNA, and hsa-miR-103 correlated with RNA yield or EV number in clinical specimens from glioblastoma patients." (PMID 24205116, 2013). "In the present study we addressed the question whether GAPDH expression is regulated by hypoxia in human glioblastoma cells in vitro and in human glioma tumor samples." (PMID 17597534, 2007). "Although we did not measure oxygenation levels directly in the human tumors, samples of which were analyzed regarding GAPDH expression, we considered low-grade astrocytoma and glioblastoma as tumor entities characterized by modest hypoxia and severe hypoxia, respectively." (PMID 17597534, 2007). "Therefore, we envisage that the main mechanism of cytotoxicity resides in the inhibition of glycolysis rather than in GAPDH aggregation, a mechanism that was associated with cell death in glioblastoma cells." (PMID 35804925, 2022). "While under conditions of hypoxia, the antitumor effect of AEAC in glioblastoma was enhanced through disrupting PPI between HSP70 and GAPDH to promote the aggregation of oxidized GAPDH." (PMID 37189349, 2023).
glioblastoma (continued). "They applied the designed assay to detect glioblastoma biomarkers CD-pan (CD9, CD63, and CD81), with EGFR, EGFRvIII and GAPDH as control markers, from supernatants of glioblastoma cells." (PMID 33276535, 2020). "We first determined the relative abundance of GAPDH mRNA, 18S rRNA, and hsa-miR-103 in EVs derived from 6 glioblastoma and 2 non-glioblastoma adherent cell lines." (PMID 24205116, 2013). "Studies on human glioblastoma and cancer cells of different origins for its molecular regulation under hypoxic condition also revealed GAPDH expression was not involved in the gene regulation." (PMID 20707929, 2010). "The results confirm our previous findings in human glioblastoma that this gene is not an attractive target for tumor therapeutic approaches because of the lack of GAPDH regulation under hypoxia." (PMID 19144146, 2009). "We observed no hypoxia-induced regulatory effect on GAPDH expression in the three glioblastoma cell lines studied in vitro." (PMID 17597534, 2007). "Because of the lack of GAPDH regulation under hypoxia, this gene is not an attractive target for tumor therapeutic approaches in human glioblastoma." (PMID 17597534, 2007). "In addition, GAPDH expression was similar in patient tumor samples of low-grade astrocytoma and glioblastoma, suggesting a lack of hypoxic regulation in vivo." (PMID 17597534, 2007).
glioma (21 papers, 2007 to 2022). A benign or malignant brain and spinal cord tumor that arises from glial cells (astrocytes, oligodendrocytes, ependymal cells). "We managed to select CoCl2 concentrations at which these obvious manifestations of hypoxia in rat C6 glioma cells were observed and found that the incubation of C6 cells with 100 μM CoCl2 caused an increase of GAPDH expression and an almost 2.2-fold elevation of the enzyme content." (PMID 33546324, 2021). "Furthermore, our study also demonstrated that an increase in HK1, PFKM, and GAPDH expression could be associated with the CNS WHO grading of gliomas." (PMID 34573317, 2021). "To substantiate the physiological significance of GAPDH aggregation in rat glioma cells, we used the CytoTox96 assay based on lactate dehydrogenase activity determination in cell medium." (PMID 33546324, 2021). "It is important that the inhibition of Hsp70 chaperoning of GAPDH with the aid of AEAC reduced the resistance of glioma cells to moderate and severe hypoxia." (PMID 33546324, 2021). "To verify hypoxic conditions in growth tumors, we analyzed the amount of HIF1α and GAPDH mRNA in glioma cells 21 days after their injection." (PMID 33546324, 2021). "The results showed that expression levels of VEGFA, HK2, JUN, LDHA, and GAPDH were significantly high in glioma with wildtype-IDH and wildtype-1p/19q codeletion." (PMID 32500034, 2020). "The relative expression levels of SNHG14 were measured in 29 paired glioma tissues and their corresponding NATs using qRT-PCR and were normalized to GAPDH." (PMID 29552296, 2018). "Our data from clinical glioma samples confirmed high heterogeneity of PDL1 expression with a range from 0.3 to 4.2 for PDL1/GAPDH mRNA ratio." (PMID 30393513, 2018). "Glioma cells treated with gp120 (100 ng/mL for 7–10 days) showed higher proliferation rates and upregulation in the expression of enolase 2, hexokinase and glyceraldehyde-3-phosphate dehydrogenase when compared to untreated cells." (PMID 30200472, 2018). "A significant increase in protein expression was observed for hexokinase (HXK), ENO2 and GAPDH in all the glioma cell lines tested." (PMID 30200472, 2018). "Antibody labeling of GAPDH, Tom20 and V-ATPase was, on average, markedly increased relative to labeling outside the C6 gliomas, an increased level extending from the tumor rim to at least 2.5 mm into the tumor." (PMID 26032618, 2015). "On averaged profiles, labeling of a marker of the glycolytic pathway, glyceraldehyde 3-phosphate dehydrogenase (GAPDH), was, as expected, greater in the glioma." (PMID 26032618, 2015). "The altered expression of GAPDH was also found in other types of neoplasia, such as human glioma, atopic bronchial epithelial cells, and squamous cervical cancer." (PMID 24776823, 2014). "According to articles published over the past two years, three of them, ACTB, GAPDH and 18S rRNA, collectively correspond to the endogenous controls applied in more than 80% of expression analyses performed on glioma tumors or cell lines." (PMID 19257903, 2009). "Expression of GAPDH represents one of the alternatives of a housekeeping gene and can be used as a loading control in experiments with glioma cells." (PMID 17597534, 2007). "For this reason, the HK1, PFKM, and GAPDH genes could be essential for the progression of glioma to malignant grades, and in this way, they could be useful biomarkers and even targets for the therapy of gliomas." (PMID 34573317, 2021). "The expression of human GAPDH was detected in the human glioma and SCA1 + HUMSCs group." (PMID 31508229, 2019). "Finally, type IV collagen/GAPDH in 20-day gliomas was higher than in 10-day tumor cells (0.33±0.06 vs 0.24±0.07; t=3.81; P<0.05)." (PMID 28678913, 2017). "The observed excess of Tom20 over GAPDH near the rim seems to fit well with the hypothesis of lactate transfer in C6 gliomas." (PMID 26032618, 2015).
glioma (continued). "Due to this, we decided to analyze the expression levels of some glycolytic genes in pediatric glioma samples of different grades, and found that the HK1, PFKM, GAPDH, and LDHAL6A genes are overexpressed in human brain glioma biopsies." (PMID 34573317, 2021). "We observed an upregulation of the key glycolytic enzymes HXK, GAPDH and ENO2 in glioma cells treated with gp120." (PMID 30200472, 2018). "Following an acute 4 hour treatment with the reducing agent DTT, all glioma lines demonstrated a marked induction of XBP-1, BiP/GRP78, and CHOP mRNAs, while maintaining steady levels of GAPDH message." (PMID 24039668, 2013). "We have shown UPR-related mRNA loading onto glioma xenograft-derived tumor polyribosomes where GRP94, BiP/GRP78 and GAPDH mRNA distributions in the gradient fractions clearly demonstrate the efficient recruitment of UPR-sensitive transcripts into the heavy-sedimenting polyribosome fractions." (PMID 24039668, 2013). "The expression levels of CLIC1 mRNA were detected in 20 glioma and 10 non-neoplastic brain tissues normalized to GAPDH." (PMID 22578365, 2012). "The expression levels of Reg IV mRNA were detected in 20 glioma and 10 non-neoplastic brain tissues normalized to GAPDH." (PMID 22713481, 2012). "In contrast to GAPDH (negative control), selective association with GFP-MSI1 was also determined for the CD44 mRNA, supporting the conserved association of MSI1 and the CD44 mRNA in glioma-derived cell models." (PMID 33291443, 2020). "Therefore, GAPDH mRNA and protein expression is not modified in response to different oxygenation, hypoxia or reoxygenation conditions in vitro in the tested cell lines and not differently expressed in human tumor glioma samples with known different levels of hypoxia." (PMID 17597534, 2007).
liver cancer (20 papers, 2008 to 2025). An epithelial or non-epithelial malignant neoplasm that arises from the liver. "In our study, GAPDH was significantly upregulated in liver cancer, and high expression of GAPDH was an independent risk factor for prognosis in patients with liver cancer, which is consistent with the literature." (PMID 34746309, 2021). "Several studies have linked GAPDH expression to liver cancer and T cell lymphoma." (PMID 36404333, 2022). "CARM1 was previously reported to suppress the glycolysis in liver cancer cells by mediating arginine 234 (R234) methylation of GAPDH, thus inhibiting the proliferation of liver cancer cells." (PMID 39567506, 2024). "Methylated GAPDH was reported to suppress glycolysis in liver cancer cells and delay tumor cell proliferation." (PMID 37653101, 2023). "In hepatic cancer cell lines, B2M, GAPDH, UBC, and HPRT1 were the first four stable nominees, respectively, and RNA18S was determined as the least stable ones." (PMID 34752497, 2021). "This amino acid is located inside the catalytic site of GAPDH, and its methylation leads to the inhibition of GAPDH activity and to the reduction of liver cancer tumorigenicity in vitro and in vivo." (PMID 32370188, 2020). "The aim of the current review is to critically evaluate, from an interventional oncology perspective, the druggability of GAPDH and its therapeutic potential in liver cancer." (PMID 22964488, 2012). "However, another study revealed that glucose starvation-induced CARM1 expression induces GAPDH hypermethylation to suppress glycolysis in liver cancer cells, indicating a tumor-suppressive role of CARM1." (PMID 40016178, 2025). "In addition, CARM1-mediated GAPDH methylation inhibits glycolysis in liver cancer cells." (PMID 34737767, 2021). "The involvement of GAPDH in several mechanisms that are associated with hepatocarcinogenesis (e.g. viral hepatitis, metabolic alterations), and the sensitivity of human HCC to targeted inhibition of GAPDH underscore the therapeutic potential of inactivating GAPDH, particularly in liver cancer." (PMID 22964488, 2012). "To confirm the hepatic origin of these metastatic lesions, we conducted immunohistochemical staining for liver cancer-related markers (ALB and AFP) with human-specific antigens (human GAPDH and human nuclear antigen) in the metastatic lesions." (PMID 40852642, 2025). "We decided to continue the study with the HepG2 line because they expressed liver-specific and hepatic cancer stem cells markers such as CD133, alpha fetoprotein, GAPDH, and albumin." (PMID 34577545, 2021). "Additionally, mRNA levels were expressed as a percentage of the corresponding glyceraldehyde-3-phosphate dehydrogenase (GAPDH) levels to appreciate the relative levels of Cx26, Cx32 and Cx43 in the liver cancer cell lines or PHH." (PMID 34830068, 2021). "For example, biological targets identified in human liver cancer cells using a library of tagged C75 analogs revealed previously unknown putative C75 targets, including protein disulfide-isomerase A3 (PDIA3), transferrin receptor (TRFC), and glyceraldehyde-3-phosphate dehydrogenase (GAPDH)." (PMID 31681794, 2019).
Huntington disease (19 papers, 2013 to 2025). Huntington disease (HD) is a rare neurodegenerative disorder of the central nervous system characterized by unwanted choreatic movements, behavioral and psychiatric disturbances and dementia. "The involvement of GAPDH has also been proved in some neurodegenerative disorders, such as Alzheimer’s, Parkinson’s, Machado–Joseph, and Huntington’s diseases, in association with abnormal neuronal apoptosis." (PMID 41226479, 2025). "The binding of GAPDH to long polyglutamine tracts in Huntington’s disease also causes the disruption of mitophagy and probably contributes to the pathogenesis of Huntington’s disease." (PMID 32370188, 2020). "Here, we uncover a new molecular mechanism underlying mitophagy driven by glyceraldehyde-3-phosphate dehydrogenase (GAPDH) under the pathological condition of Huntington’s disease (HD) caused by expansion of polyglutamine repeats." (PMID 26268247, 2015). "As such, disruption of GAPDH function may lead to the accumulation of damaged mitochondria and apoptosis, as observed in Huntington’s Disease (HD)-associated pathology." (PMID 33946782, 2021). "The expression of the CerS1 primary band (∼40 kDa) was lower in Huntington’s disease caudate compared to controls when adjusted for both β-actin (−57.60%, P = 0.0025) and GAPDH (−23.34%, P = 0.0098)." (PMID 35169703, 2022). "In a transgenic model of Huntington’s disease, GAPDH is seen to be overexpressed in specific neuronal populations of several brain regions, such as the neocortex and caudate putamen neurons." (PMID 25520698, 2014). "ThesiRNA technology was used to show that the inhibition of GAPDH expression leadsto a 45–50% reduction in the aggregation of mutant huntingtin, with a repeat of103 glutamine residues in a model of Huntington’s disease (HD)." (PMID 23819039, 2013). "Finally, based on pathway, three genes were associated with cytoskeletal regulation by Rho GTPase pathway (ACTB, PFN1 and CFL1) while two genes were associated each with glycolysis (GAPDH and PGK1) and Huntington disease (GAPDH and ACTB)." (PMID 34681026, 2021). "In a cellular model of Huntington's disease, the DNM3OS/miR-196b-5p/GAPDH pathway was found to be involved in the molecular pathogenesis of the disease." (PMID 38152068, 2023). "Glyceraldehyde 3-phosphate dehydrogenase (GAPDH), also not a member of any canonical mitophagy genesets/pathways, promotes the fusion of damaged mitochondria with lysosome, thus promoting mitophagy in Huntington's disease." (PMID 37358952, 2023).